BCL2L2 (BCL2 like 2)
Diseases named in the same sentence as BCL2L2 in open-access papers (continued):
Sharing a sentence is not in itself a finding about the gene and the disease.
glioma (4 papers, 2007 to 2022). A benign or malignant brain and spinal cord tumor that arises from glial cells (astrocytes, oligodendrocytes, ependymal cells). "Indeed, bcl-w/bcl2l2 (bcl-2-like protein 2) gene encodes an anti-apoptotic protein which expression is regulated by DNA methylation in glioma." (PMID 31727122, 2019). "We performed paired‐end RNA‐seq of rat C6 glioma cells and normal cells and discovered a read‐through fusion transcript Bcl2l2‐Pabpn1 in which exon 3 of Bcl‐2‐like protein 2 (Bcl2l2) fused to exon 2 of Polyadenylate‐binding protein 1 (Pabpn1)." (PMID 35894779, 2022). "Excitingly, Bcl2l2‐Pabpn1 fusion was detected both in human glioma cells and human primary astrocytes (HA cells)." (PMID 35894779, 2022). "The results relative to BCL2L2 expression in various types of human glioma cancers published here are partially based upon data generated by The Cancer Genome Atlas pilot project established by the NCI and NHGRI." (PMID 26155940, 2015). "Some genes already described as related to glioma's invasion capacity by microarray studies such as SPOCK1, BCL2L2, EEF1A2 and TMEFF1 also appeared in the 50 first best triples." (PMID 17519038, 2007). "Unlike other fusions reported in glioma, Bcl2l2‐Pabpn1 appeared to be generated by RNA processing without DNA rearrangement." (PMID 35894779, 2022).
hepatocellular carcinoma (4 papers, 2014 to 2021). A malignant tumor that arises from hepatocytes. "Multiple miR-125b targets were found to be upregulated in hepatocellular carcinoma, including BCL2, BCL2 like 2 (Bcl-W), myeloid cell leukemia sequence 1 (Mcl-1), interleukin-6 receptor (IL6R), lin-28 homolog B (LIN28B) and placenta growth factor (PIGF)." (PMID 24774301, 2014). "According to previous reports, miR-29b suppresses angiogenesis, invasion, and metastasis by inhibiting MMP-2 expression in hepatocellular carcinoma; however, to our knowledge, no study has examined the relationship between miR-29 and BCL2L2 expression and their effect on GBM cell phenotype." (PMID 26155940, 2015).
Sepsis (3 papers, 2020 to 2025). Sepsis is defined as life-threatening organ dysfunction caused by a dysregulated host response to infection. "lncRNA colorectal neoplasia differentially expressed (CRNDE) exerts a protective impact on liver injury caused by sepsis through miR-126-5p/BCL2 like 2 (BCL2L2)." (PMID 34592882, 2021). "As microRNA sponges, CRNDE regulates the biological function of miR-126-5p, promotes the expression of BCL2L2, and alleviates liver damage induced by sepsis." (PMID 33204219, 2020). "Sepsis-induced overexpression of METTL3 promotes the maturation of miR-193a, which binds to the 3’UTR of BCL2L2, resulting in the downregulation of BCL2L2." (PMID 41373022, 2025).
leukemia (2 papers, 2011 to 2020). A malignant (clonal) hematologic disorder, involving hematopoietic stem cells and characterized by the presence of primitive or atypical myeloid or lymphoid cells in the bone marrow and the blood. "There are no reports connecting BCL2L2 with leukemia, yet some reports refer to its pro-survival role in leukemogenesis." (PMID 22185641, 2011).
lung adenocarcinoma (2 papers, 2021 to 2024). A carcinoma that arises from the lung and is characterized by the presence of malignant glandular epithelial cells. "In the TCGA dataset of lung adenocarcinoma, expression of MCL1, BCL2, BCL2L2, and BCL2A1 was significantly higher in non-tumor relative to tumor cells." (PMID 39122703, 2024).
lymphoma (2 papers, 2019 to 2020). A malignant (clonal) proliferation of B- lymphocytes or T- lymphocytes which involves the lymph nodes, bone marrow and/or extranodal sites. "Targeting BCL2L2 by shRNA induced apoptosis in lymphoma cell lines and higher levels of BCL2L2 in patients with B lymphocyte leukemia are associated with lower overall survival." (PMID 32580769, 2020). "Furthermore, BCL2L2 is significantly overexpressed in aggressive and indolent lymphomas." (PMID 32580769, 2020).
atopic dermatitis (1 paper, 2022). "This microRNA promotes keratinocyte apoptosis by inhibiting Bcl2L2 (Bcl-2-like protein 2) protein, contributing to epithelial barrier dysfunction typically impaired in atopic dermatitis." (PMID 35563264, 2022).
autoimmune disease (1 paper, 2021). A disorder resulting from loss of function or tissue destruction of an organ or multiple organs, arising from humoral or cellular immune responses of the individual to their own tissue constituents. "For instance, Bcl2l2 and Birc5 expression was observed throughout the small pre-B cell stage but it was lost in immature B cells in mice without an autoimmune disease genetic background." (PMID 33557010, 2021).
brain cancer (1 paper, 2007). A primary or metastatic malignant neoplasm affecting the brain. "The biological role of Fn14 in brain cancer progression was correlated to Fn14 activation and induction of BCL2L2 mRNA and protein levels, and this effect depended on NFkappaB transcriptional activity." (PMID 17519038, 2007).
brain injury (1 paper, 2012). Acute and chronic (see also brain INJURIES, CHRONIC) injuries to the brain, including the cerebral hemispheres, CEREBELLUM, and brain STEM. "Furthermore, a recent study shows that upregulated miR-29b promotes neuronal cell death by inhibiting Bcl2L2 after ischemic brain injury." (PMID 23272113, 2012).
Burkitt lymphoma (1 paper, 2020). A rare form of malignant mature B-cell non-Hodgkin lymphoma. "A high expression of BCL2L2 was assessed in diffuse large B-cell lymphoma (DLBCL) and in almost 90% of patients with Burkitt lymphoma (BL)." (PMID 32317622, 2020).
chronic lymphocytic leukemia (1 paper, 2020). "BCL2L2 was identified as a target of p65/NF-κB in chronic lymphocytic leukemia cells, which was confirmed in experiments involving BAY110782, an inhibitor of NF-κB38." (PMID 32317622, 2020).
cognitive decline (1 paper, 2020). "For example, BCL2L2 was the potential target gene of both hsa_circRNA_001145 and hsa_circRNA_061570, the differential expression of which was reported to induce systemic inflammation and cognitive decline." (PMID 32655392, 2020).
Diverticular disease of (1 paper, 2024). "Across significant (FDR < 0.25) gene/trait associations, the largest magnitude of effect was the association of diverticular disease with lower expression of BCL2L2, encoding BCL-W." (PMID 38589365, 2024). "Remarkably, we detected significant associations between BAK1 and Rheumatoid arthritis/Polyarthropathies (p = 2.50e-3) as well as BCL2L2 and Diverticular disease of the intestine (p = 3.86e-02)." (PMID 38589365, 2024).
hypoxic-ischemic-encephalopathy (1 paper, 2021). "In relation to BCL2L2, BNIP3 (FC = 1.17, p = 0.04) encodes BCL2 interacting protein 3, which is increased in hypoxic-ischemic-encephalopathy and physiological ageing, and has been shown to increase in association with cellular senescence especially in cells over-expressing p21 and p16." (PMID 33964983, 2021).
melanoma (1 paper, 2010). A malignant, usually aggressive tumor composed of atypical, neoplastic melanocytes. "The majority of PAX3-positive cells in melanomas, naevi and normal skin co-express BCL2L2 at a similar frequency." (PMID 20421967, 2010). "As expected we have observed positive BCL2L2 staining in all normal skin, naevi and primary melanoma samples analysed." (PMID 20421967, 2010).
oculopharyngeal muscular dystrophy (1 paper, 2021). Oculopharyngeal muscular dystrophy (OPMD) is an adult-onset progressive myopathy characterized by progressive eyelid ptosis, dysphagia, dysarthria and proximal limb weakness. "BCL2L2-PABPN1 is a paralog of PABPN1, which is associated with the development of oculopharyngeal muscular dystrophy, a disease characterized by muscular weakness in eyelids, pharyngeal musculature, and limbs." (PMID 34440365, 2021).
PNS tumors (1 paper, 2025). "= 0.471) between the essentiality of Wsb2 and Bcl2l2 in PNS tumors." (PMID 40832228, 2025).
cancer (29 papers, 2010 to 2025). A tumor composed of atypical neoplastic, often pleomorphic cells that invade other tissues. "Metascape database analysis revealed that the target mRNAs PRKACB and PDCD4 of miR-550a-3p as well as RPS6KA5 and BCL2L2 of miR-550a-5p were associated with miRNA cancer pathway, providing important clues for subsequent studies on the mechanism underlying EAC development." (PMID 36829221, 2023). "A total of 20 target mRNAs of three miRNAs were predicted, among which seven target mRNAs—ASAP3, BCL2L2, LMF1, PPM1L, PTPN21, SLC18A2, and NR3C2—had prognostic value; PRKACB, PDCD4, RPS6KA5, and BCL2L2 were enriched in the miRNA cancer pathway." (PMID 36829221, 2023). "Many studies indicate that miR-122 represses Bcl-w (BCL2L2) expression in various cancer cell lines, including HCC." (PMID 35890276, 2022). "Multiple studies have reported that BCL2L2 enhanced cell migration and invasion in several forms of cancers." (PMID 34620126, 2021). "B cell lymphoma-2-like 2 protein (BCL2L2) belongs to the BCL2 family that exerts an important role in human cancers." (PMID 34620126, 2021). "BCL2L2 oncogene is frequently overexpressed in many malignant tumors, and as an important regulator of cell proliferation, survival, and metastasis, it has been identified as a key downstream target of miR-335." (PMID 34090463, 2021). "As a member of the Bcl-2 family, BCL2L2 is similar to its close relative Bcl-2, and is involved in the carcinogenesis and progression in human cancers." (PMID 29358307, 2018). "Altogether, these analyses support the notion of a molecular system whereby miR-29b inhibits aggressive GBM development via BCL2L2 inhibition, and implicate miR-29b as a potential candidate in anti-cancer therapy." (PMID 26155940, 2015). "To confirm this prediction, we had measured miR-29b and BCL2L2 protein or mRNA levels in various cancer cells and noted an inverse relationship between the two, which supported BCL2L2 as a direct target of miR-29b." (PMID 26155940, 2015). "These miRNAs target the tumour suppressor genes, PTEN, TP53INP1 and TP53INP2, and other proteins involved in cancer development and progression, such as BCL2L2, ERBB4, MAPK9, MCL1, MYCN, VEGFA and VEGFR1." (PMID 20668671, 2010). "Moreover, BCL2L2 constrained the tumorigenesis of human cancers, like hepatocellular carcinoma and non-small cell lung cancer." (PMID 34620126, 2021). "Therefore, we propose that miR-29b has potential as an anti-cancer therapy in GBM by targeting oncogenic BCL2L2." (PMID 26155940, 2015). "Furthermore, miR-29b expression was inversely proportional to that of BCL2L2 mRNA or protein in various cancer cell types." (PMID 26155940, 2015). "Overexpression of anti-apoptotic or pro-survival proteins of the Bcl family such as Bcl 2, B-cell lymphoma-extra large (Bcl-xL), myeloid cell leukemia 1 (Mcl-1), Bcl-2-like protein 2 (BCL2L2 or Bcl-w) and Bcl-2-related protein A1 (A1/Bfl-1) has been reported to be present in cancer." (PMID 26563258, 2015). "This supported our hypothesis for BCL2L2 in promoting cancer cell migration, invasion, and EMT." (PMID 26155940, 2015). "For example, BCL2L2 (protein 2 similar to BCL2, also known as BCL-w), myeloid leukemia 1, and BCL2 are observed to be overexpressed in various kinds of cancers, leading to carcinogenesis and apoptosis inhibition." (PMID 34090463, 2021). "Conversely, BCL2, BCL2L2, and MCL1 show downregulation across 2‐3 different cancer types, despite distal BCL2 regulation." (PMID 32419250, 2020). "Targeting to CDCA4, BCL2L2, YAP1, AKT-3 and Cyclin E1, miR-15a has been found to significantly reduce cancer cell survival and aggressiveness." (PMID 30733644, 2019). "Current evidence suggests that the B-cell lymphoma 2 homolog, BCL2-like 2 (BCL2L2; also known as Bcl-w) enhances tumorigenicity and cell survival through its anti-apoptotic activity in cancer cells." (PMID 26155940, 2015).
cancer (continued). "Because miR-195 is involved in repression of cell cycle accelerators (CCND1, CCNE1, CDK4, CDK6, and E2F3) and anti-apoptotic factors (BCL2, BCL2L2, and BIRC5), miR-195 functions as a tumor suppressor miRNA in various types of human cancers." (PMID 25364765, 2014). "Downregulation of anti-tumor (tumor suppressor) miR-125b in human cancers promotes survival, proliferation and invasion of tumor cells through de-repression of BCL2, BCL2L2, E2F3, ERBB2, FGFR2, MCL1, SIRT7, Smoothened and STAT3." (PMID 25364765, 2014). "We also have found that miR-29a can potentially target BCL2L2, VEGFA and CDK6, which are involved in cancer initiation and progression." (PMID 20668671, 2010). "In contrast to these three main anti-apoptotic BCL2 proteins, the genes for the related anti-apoptotic BCL2 proteins Bfl1 (BCL2A1), BCL-w (BCL2L2) and BCL-B (BCL2L10) display little perturbation effects in cancer (mean Chronos Gene Dependency Scores −0.0454, −0.103 and 0.006, respectively)." (PMID 40113751, 2025). "For example, antiapoptotic proteins, such as BCL-2, BCL2L2 and MCL1, can block autophagy in cancer." (PMID 36768482, 2023). "Although this fusion was reported in human cells in the database (provided by RefSeq, Dec 2010), it has not been characterized in rat cells and there is no investigation about the roles of Bcl2l2‐Pabpn1 in cancers." (PMID 35894779, 2022). "Genetic alterations in BCL2L2 contributes to many cancers such as copy number variations in small and non-small lung cancer, high level of BCL-w contributes to gastric carcinomas, and low BCL-w expression contributes to colorectal cancer." (PMID 35951173, 2022). "Finally, we have identified a number of down-regulated miRNAs whose targets are up-regulated in cancer, including the oncogenic protein KRAS and MYCN, mitogen-activated protein (MAP) kinases and the anti-apoptotic proteins BCL2, BCL2L2 and MCL-1 among others." (PMID 20668671, 2010). "To test this hypothesis using cancer cell lines identified in the present study to be less sensitive to fadraciclib, we determined the effects of fadraciclib combined with BCL2 inhibitor venetoclax (ABT-199), or BCL2/BCL2L1/BCL2L2 (bcl-w) inhibitors ABT-263 or ABT-737 in THP-1." (PMID 32645016, 2020). "While MCL1, BCL2L1, or BCL2L2 were ubiquitously expressed, BCL2 and BCL2A1 demonstrated tissue/lineage-selective expression with very low/no expression across most of the cancer cell lines and TCGA tumor tissues." (PMID 30635584, 2019).
tumor (22 papers, 2013 to 2025). "A significant way miR-422a exerts its tumor-suppressive effects is by targeting BCL2L2, an anti-apoptotic gene that maintains tumor cell survival." (PMID 40429954, 2025). "The key finding of our study is that the release of mtDNA from pyroptotic tumor cells is crucial for the activation of macrophages, and we also identified BCL2L2 as a SF3B1 target gene that plays a role in pyroptosis." (PMID 38012150, 2023). "With the overexpression of miR‐335‐5p or the downregulation of BCL2L2 expression, cisplatin sensitivity can be significantly improved and tumor growth can also be greatly reduced." (PMID 30019389, 2018). "It was observed that the tumor size was significantly smaller in mice treated with DDP when miR‐335‐5p was upregulated or BCL2L2 was downregulated." (PMID 30019389, 2018). "Bcl2l2‐Pabpn1 fusion was expressed widely in human normal and tumour tissues (provided by RefSeq, Dec 2010), suggesting that Bcl2l2‐Pabpn1 read‐through may be a candidate fusion transcript shared by rats and humans." (PMID 35894779, 2022). "More importantly, BCL2L2 can promote tumor development by increasing cell proliferation in OSCC." (PMID 34620126, 2021). "In addition, our results demonstrate that miR-422a functions as a tumor suppressor by directly targeting BCL2L2 and KRAS." (PMID 29358307, 2018). "All these results showed that miR‐335‐5p could suppress cell viability and enhance cell apoptosis of cisplatin‐resistant tumor cells through downregulating BCL2L2." (PMID 30019389, 2018). "Finally, we confirmed that BCL2L2 repression is of central importance to miR-29b anti-tumor activity using functional assays to examine cell migration, invasion, angiogenesis, and stemness." (PMID 26155940, 2015). "BCL2-like 2 (BCL2L2) was found as a key link regulated through splicing regulation by SF3B1, and mitochondrial DNA (mtDNA) released from tumor cells with pyroptosis played a crucial part in polarization of macrophages and infiltration of cytotoxic lymphocytes." (PMID 38012150, 2023). "Tumor volume and weight were also lower in A2780/DDP + miR‐335‐5p mimics + DDP group and A2780/DDP + BCL2L2 siRNA + DDP group than in A2780/DDP + miR‐335‐5p mimics + BCL2L2 siRNA + DDP group (P < 0.01)." (PMID 30019389, 2018). "In order to ascertain the anti-tumor property of miR-422a is mediated by inhibition of BCL2L2 and KRAS, four siRNA specific for BCL2L2 (si-39, si-72, si-75, si-98) and KRAS (si-52, si-92, si-118, si-177) were generated using siRNA Selection software." (PMID 29358307, 2018). "Depletion of the NCOA3-p300-NF-κB components or blockage of NCOA3 function with inhibitors (gossypol and bufalin) in ER-positive cells suppressed BCL2, BCL2A1, BCL2L2, and MCL1 expression, while also decreasing cell viability, colony formation, cell invasion, and tumor growth." (PMID 36853387, 2023). "The CNVkit SCNA analysis also highlights the potential importance of oncogenes (e. g., RCP, CD44, WT1, BCL2L2, and AKT2) and tumor suppressors (e. g., PRKCDBP) to TNBC etiology and metastatic progression, as significant amplicons/deleted regions harbor these genes." (PMID 35992833, 2022). "The BCL2L2 of the Bcl-2 family is an important anti-apoptotic gene, and suppression of its expression sensitizes cells to anticancer drugs, whereas MT1F exerts its tumor-suppressive ability by inducing apoptosis." (PMID 24019915, 2013). "Furthermore, Bcl2 and Bcl2l2 expression in tumor cells were relatively low and not increased by EGFR-TKI treatment." (PMID 39122703, 2024). "However, there was a limitation that we did not analyze the influence of miR-216a-5p/BCL2L2 axis on xenograft tumor growth in vivo, which will be studied in future work." (PMID 34620126, 2021). "Upregulation of the anti-apoptotic genes BCL2L2, BAG3, and downregulation of pro-apoptotic genes DAXX, FAF1, PAK1, DFFA, ENDOG was found in reprogrammed tumours pointing to a cell cycle arrest without engagement of the apoptotic pathway." (PMID 29662623, 2018).
liver (1 paper, 2022). "LncRNA CRNDE also acted as an endogenous competing RNA to adsorb miR-126–5p, promoting the expression of BCL2L2, and finally could attenuate septic liver injury by inhibiting hepatocyte apoptosis." (PMID 36386180, 2022).
BCL2L2 also shares sentences with these, for which no sentence is quoted: prostate carcinoma (3 papers); acute myeloid leukemia (2); angiosarcoma (1); asthma (1); B cell lymphoma (1); breast tumor (1); Cognitive impairment (1); colorectal cancer (1); diffuse large B-cell lymphoma (1); Hodgkins lymphoma (1); Hyperglycemia (1); idiopathic pulmonary fibrosis (1); inflammatory skin disease (1); Insulin resistance (1); kidney cancer (1); Lupus (1); myeloma (1); myocardial hypertrophy (1); non-small cell lung carcinoma (1); Obesity (1); oral cancer (1); oral squamous cell carcinoma (1); Polyarthropathies (1); rheumatoid arthritis (1); Thrombocytopenia (1); tongue SCC (1).